STAT6 (signal transducer and activator of transcription 6)
Diseases named in the same sentence as STAT6 in open-access papers (continued):
Sharing a sentence is not in itself a finding about the gene and the disease.
psoriasis (6 papers, 2021 to 2025). An autoimmune condition characterized by red, well-delineated plaques with silvery scales that are usually on the extensor surfaces and scalp. "The formula also influenced the production of key cytokines and markers associated with M1 and M2 macrophages through the STAT1 and STAT6 pathways, highlighting its potential in psoriasis treatment." (PMID 40539722, 2025). "Expression of this miRNA has also been found to be over-expressed in both psoriasis patients and psoriasis animal models where it stimulates Th17 and Th1 cell differentiation but suppresses Th2 differentiation via inhibiting expressions of STAT6 and LYN." (PMID 34804042, 2021). "In conclusion, our findings suggested that Foxp3− Treg‐of‐B cells could induce alternatively activated M2 macrophages through STAT6 activation, providing a cell‐based therapeutic strategy for psoriasis." (PMID 37073709, 2023). "Both GATA3 and STAT6 may act in concert with the Notch signaling pathway to control an optimal Th2 cell response during psoriasis, in which GATA3 is the central regulator for maintaining the effectiveness of Th2 response." (PMID 37270497, 2023). "Treatments involving Treg‐of‐B cells activate M2 macrophages via the STAT6 pathway, reducing TNF‐α and IL‐6 production and alleviating psoriasis symptoms in mice." (PMID 40539722, 2025). "Likely, the IL-4/STAT6 and IL-4/GATA3 signaling pathways prevent hyperactive Th1 responses in psoriasis." (PMID 37270497, 2023). "MiR-210 was reported to be increased and to regulate Th17 and Th1 cells by inhibiting the expression of STAT6 and LYN in psoriasis." (PMID 34140947, 2021).
schwannoma (6 papers, 2014 to 2026). A benign, usually encapsulated slow growing tumor composed of Schwann cells. "On the other hand, in comparison with both CD13 and EMA, SOX10 expression significantly supported a diagnosis of schwannoma (p < 0.0001) as well as STAT6 staining that of SFT/HPC (p < 0.0001)." (PMID 35212813, 2022). "All of the retrieved schwannomas stained positive for SOX10 (15/15), as well as all the SFT/HPCs for STAT6 (20/20)." (PMID 35212813, 2022). "Both neurofibroma and schwannoma are positive for SOX10 and S100 protein, negative for STAT6; meanwhile, neurofibroma is also positive for CD34." (PMID 41226013, 2025).
acute myeloid leukemia (5 papers, 2014 to 2025). Acute myeloid leukemia (AML) is a group of neoplasms arising from precursor cells committed to the myeloid cell-line differentiation. "It has previously been shown that Ang-1 can stimulate phosphorylation of STAT-1, STAT-3, STAT-5 and STAT-6 in human acute myeloid leukemia cells, although the physiological consequences of this were not identified." (PMID 24404127, 2014). "Furthermore, IL-4 triggers apoptosis in acute myeloid leukemia cells through a Stat6-dependent pathway." (PMID 40362656, 2025). "Besides, in acute myeloid leukemia (z score = −2.03, p = 0.0421), a higher CTL level indicated a better prognosis when STAT6 had higher expression." (PMID 36968603, 2023).
dermatofibrosarcoma protuberans (5 papers, 2020 to 2025). Dermatofibrosarcoma protuberans (DFSP) is a rare infiltrating soft tissue sarcoma, generally of low grade malignancy, arising from the dermis of the skin and characteristically associated with a specific chromosomal translocation t(17;22). "STAT6 staining plays a pivotal role in differentiating SFTs from histological mimics, as nuclear STAT6 positivity is a key diagnostic feature identifying SFTs from tumors like dermatofibrosarcoma protuberans and myxoid liposarcoma." (PMID 40308427, 2025). "Dermatofibrosarcoma protuberans were CD34 diffusely positive and STAT6 negative." (PMID 32566457, 2020). "Dermatofibrosarcoma protuberans are often CD34 diffuse positive and STAT6 negative." (PMID 32566457, 2020).
diffuse large B-cell lymphoma (5 papers, 2021 to 2024). "STAT6 is also mutated in 11–36% of diffuse large B-cell lymphomas (DLBCL), follicular lymphomas (FL), and primary mediastinal B-cell lymphomas (PMBCL)." (PMID 36671496, 2023). "An earlier study suggested that 20 of 55 (36%) PMBL cases harbor heterozygous missense mutations in the STAT6 DNA-binding domain, whereas no mutation in the gene was found in 25 diffuse large B-cell lymphoma samples." (PMID 34925435, 2021). "The first group included patients [three patients with diffuse large B-cell lymphoma (DLBCL) and one patient with Burkitt lymphoma] who exhibited gain of chromosome 12, which is where STAT6, MDM2, and BCL7A are located." (PMID 34710202, 2021).
endometriosis (5 papers, 2019 to 2026). The growth of functional endometrial tissue in anatomic sites outside the uterine body. "Using a co-culture system, we simulated a cholesterol-abundant ectopic milieu and demonstrated cholesterol induced M2 macrophage polarization via the STAT6/PPARγ pathway, connecting cholesterol metabolism to immune response in endometriosis." (PMID 41362733, 2026). "In the complex microenvironment of endometriosis, except for exerting a direct promoting impact on EESCs, cholesterol drives the polarization of macrophages towards the M2 phenotype through the STAT6/PPARγ signaling pathway." (PMID 41362733, 2026). "In general, targeting the IL-34/CSF1R/JAK3/STAT6 pathway with a STAT6 inhibitor was an effective means of treating endometriosis in rats." (PMID 31727934, 2019). "In summary, our results demonstrated that cholesterol accumulation in endometriotic lesions directly promotes ESCs proliferation and invasion, and stimulates M2 macrophage polarization via the STAT6/PPARγ signaling pathway, creating a microenvironment conducive to endometriosis progression." (PMID 41362733, 2026). "IL-4 and IL-13 type I and II receptor signaling pathways are linked to Signal Transducer and Activator of Transcription 6 (STAT6) expression, responsible for mediating IL-4 and IL-13 immune signaling, increase proliferation, adhesion and viability of endometriosis lesions." (PMID 36120440, 2022). "Unsurprisingly, IL-34, VEGF, MMP-2 and MMP-9 were increased in the sera of the experimental endometriosis rats, which could be abrogated by STAT6 signaling blockage with AS1517499." (PMID 31727934, 2019). "In summary, autocrine production of IL-34, mediated by STAT6, promoted the development of endometriosis in vitro and in vivo through the CSF1R/JAK3/STAT6 pathway." (PMID 31727934, 2019). "Further, an IL-34 neutralizing antibody could attenuate CSF1R/JAK3/STAT6 activation and down-regulate VEGF, MMP-2 and MMP-9, eventually leading to suppression of the development of endometriosis in vitro." (PMID 31727934, 2019).
hematoma (5 papers, 2022 to 2024). A hematoma is a collection of blood from a vascular structure into an extravascular space. "Transcriptomic analyses revealed diminished expression of IL-1 receptor-like 1 (ST2) in microglia/macrophages of STAT6 KO mice post-ICH, underscoring the significance of IL-4/STAT6/ST2 signaling in hematoma resolution and functional recovery after ICH." (PMID 39660125, 2024). "A small number of studies have demonstrated that IL-4 treatment after ICH promotes hematoma absorption, relieves neuroinflammation, and enhances neural functional recovery through the STAT6 signaling pathway." (PMID 36970539, 2023). "Recently, IL-4/STAT6 signaling accelerated microglia-and macrophage-mediated hematoma clearance and improved neurofunctional recovery following ICH in blood and collagenase injection models." (PMID 36439158, 2022). "The limited available data indicates that IL-4, as an anti-inflammatory factor, may induce the differentiation of anti-inflammatory microglia (also known as M2 microglia) through the STAT6 signaling pathway and mediate the phagocytosis of hematoma components." (PMID 36970539, 2023).
Hepatic steatosis (5 papers, 2020 to 2025). Steatosis is a term used to denote lipid accumulation within hepatocytes. "In addition, rosiglitazone limited liver steatosis while enhancing adipose fat accumulation and insulin sensitivity in STAT6-deficient mice, suggesting a complex interaction between STAT6 and PPAR-γ in the regulation of whole-body fat distribution." (PMID 41409600, 2025). "Accordingly, another study demonstrated that exogenous IL-25 administration protects against hepatic steatosis through IL-13-induced activation of STAT6." (PMID 41409600, 2025). "Inhibit T-box (T-bet) in T cells and increase the activation of transcription 6 (STAT6) phosphorylation, thus regulating the Th1/Th2 response, inhibiting pro-inflammatory cytokines expression and reversing hepatic steatosis." (PMID 37361209, 2023). "What we do know is that the IL‐4/STAT6 pathway has been shown to increase glucose oxidation by inhibiting PPARα activity in hepatocytes, while knockout of STAT6 promotes hepatic steatosis and IR." (PMID 37303813, 2023). "IL-25 promotes hepatic macrophage differentiation towards the M2a phenotype, both in vivo and in vitro, via the IL-13/STAT6 pathway, alleviating HFD-induced hepatic steatosis." (PMID 41409600, 2025).
intracerebral hemorrhage (5 papers, 2019 to 2024). A cerebrovascular disorder characterized by bleeding into one or both cerebral hemispheres including the basal ganglia and the cerebral cortex. "Interleukin-4 (IL-4) serves as a canonical activator of signal transducer and activator of transcription 6 (STAT6), and exogenous IL-4 administration has been shown to activate STAT6 and enhance erythrophagocytosis in intracerebral hemorrhage (ICH)." (PMID 39660125, 2024). "Transcription analysis showed that IL‐1 receptor‐like 1 (ST2) expression level in STAT6 KO mice microglia/macrophages decreased after intracerebral hemorrhage." (PMID 37786889, 2022). "STAT6 is also a key enhancer of erythrocyte engulfment after intracerebral hemorrhage, and the IL‐4/STAT6 axis promotes long‐term recovery in models of ICH." (PMID 35751629, 2022). "STAT6 KO abated the ability of phagocytic cells to phagocytic brain tissue after intracerebral hemorrhage and primary cultured red blood cells." (PMID 37786889, 2022). "The construction of chimeric mice with bone marrow showed that STAT6 KO could worsen the prognosis of intracerebral hemorrhage in both the periphery and the central nervous system." (PMID 37786889, 2022). "IL-4 may partially promote M2 microglia/macrophage polarization through the JAK1/STAT6 pathway, therefore reducing neuroinflammation after intracerebral hemorrhage." (PMID 35204186, 2022).
non-small cell lung carcinoma (5 papers, 2011 to 2025). A group of at least three distinct histological types of lung cancer, including non-small cell squamous cell carcinoma, adenocarcinoma, and large cell carcinoma. "Clinical pathological analyses reveal that approximately 54% of non-small cell lung cancers exhibit high STAT6 expression levels, with this abnormal expression pattern being particularly prominent in immune cell populations infiltrating the pulmonary interstitium." (PMID 41585886, 2025).
pneumonia (5 papers, 2017 to 2022). An acute, acute and chronic, or chronic inflammation focally or diffusely affecting the lung parenchyma, caused by an infection in one or both of the lungs (by bacteria, viruses, fungi, or mycoplasma.). "In vivo experiments probing a pre‐clinical pneumonia mouse model demonstrated increased clearance of K. pneumoniae following the inhibition of STAT6." (PMID 36337046, 2022). "The transition of M1 to M2 macrophages during the late stages of pneumonia mediates the inflammation resolution via producing IL-4 and IL-13, which promote STAT6 activation." (PMID 32849610, 2020). "Thus, TSG-6 activates STAT6 to induce Gas6 expression in AMs for the ALI resolution during pneumonia." (PMID 32849610, 2020).
tendon disease (5 papers, 2019 to 2025). "We previously identified macrophage phenotype is complex and plastic in human tendon disease, demonstrating macrophages exhibit interferon, NF- κB, STAT-6 and glucocorticoid receptor activation states." (PMID 32179829, 2020). "Suppression of STAT-6 signaling may modulate IL-4 and IL-13 responsive genes known to drive fibrosis in the advanced stages of tendon disease." (PMID 30916999, 2019). "In early-stage tendon disease tissues, downstream signaling pathways of M1 and M2 such as IFN and STAT-6 are activated, while in the late stage, the M2 pathway is activated." (PMID 40391077, 2025).
Ureteral obstruction (5 papers, 2020 to 2024). Obstruction of the flow of urine through the ureter. "Stat6 has previously been reported as regulator of cyst growth in polycystic kidney disease and implicated in kidney fibrosis in a model of unilateral ureteral obstruction, yet further data on sex differences and functional role in podocytes are still lacking." (PMID 39278930, 2024). "In a mouse model of unilateral ureteral obstruction, the activation of signal transducer and activator of transcription 6 (STAT6) inhibits FAO, leading to lipid accumulation and the development of fibrosis." (PMID 37814303, 2023). "Specifically, STAT6 was activated along with the accumulation of lipids via the downregulation of FAO-related genes when mice were subjected to unilateral ureteral obstruction (UUO) or high-fat diet challenge." (PMID 35046382, 2022). "Of note, the total STAT6 levels in the kidney are increased following ureteral obstruction or folic acid administration, which is somewhat reduced after AS1517499 treatment." (PMID 34512669, 2021). "Unilateral ureteral obstruction or folic acid administration induced STAT6 activation in interstitial cells of the kidney, which was significantly abolished by AS1517499 treatment." (PMID 34512669, 2021).
acute lymphoblastic leukemia (4 papers, 2018 to 2025). Leukemia with an acute onset, characterized by the presence of lymphoblasts in the bone marrow and the peripheral blood. "DNR-induced apoptosis of acute lymphoblastic leukemia cells is increased by the loss of the signal transducer and activator of transcription 6 (STAT6)." (PMID 30388783, 2018).
astrocytoma (4 papers, 2011 to 2021). "Lung type I cell membrane-associated glycoprotein, also known as podoplanin, has been implicated in promoting invasion of astrocytomas; its expression also declines following STAT6 knockdown in U-87MG." (PMID 21595984, 2011). "In previous studies, PIBF (200 ng/mL) increased the number of astrocytoma cells through the activation of the IL-4Rα/JAK1/STAT6 pathway." (PMID 28168193, 2017). "STAT6 was detected by IHC in the majority of human astrocytoma specimens ranging from Grade I (pilocytic astrocytoma) to Grade IV (GBM), but notably not in any normal brain sections." (PMID 21595984, 2011). "The fact that STAT6 over-expression is consistently maintained in high-grade astrocytomas does imply possible additional functions for STAT6, potentially involving tumor maintenance and/or progression." (PMID 21595984, 2011). "We validated the relevance of our in vitro findings by assessing STAT6 expression in human patient astrocytoma specimens of different malignancy." (PMID 21595984, 2011). "Comparison of STAT6 expression between Grades I-IV astrocytomas and normal brain on the TMA." (PMID 21595984, 2011). "In our TMA study, STAT6 immunostaining was visible in the majority of astrocytomas of all grades (I-IV) but not in normal brain tissue." (PMID 21595984, 2011). "STAT6 was also downregulated in astrocytoma, but not in oligodendroglioma." (PMID 31530290, 2019).
Burkitt lymphoma (4 papers, 2021 to 2024). A rare form of malignant mature B-cell non-Hodgkin lymphoma. "Lastly, STAT6 is activated in response to IL-4 and IL-13 via phosphorylation at Tyr641 and, in Daudi cells (also called Burkitt lymphoma) after stimulation with IFN-α, STAT6 forms an unusual heterodimer with STAT5 protein." (PMID 38396958, 2024). "Similarly, pentagalloylglucose and tannic acid impaired IL-4/STAT6 signaling in Burkitt lymphoma cells." (PMID 36012541, 2022).
depression (4 papers, 2022 to 2025). "In addition, in terms of neuroinflammation, STAT6 was found to be associated with neurodegeneration diseases, including depression." (PMID 36009493, 2022). "Previous studies using animal models emphasized that a deficiency of STAT6 decreases levels of dopamine and serotonin transporter; thus, STAT6 is suggested to play a pivotal role in the pathogenesis of depression through monoamine regulation in the hippocampus of the brain." (PMID 36009493, 2022). "Several previous studies support the role of STAT6 in depression; these were validated in a preclinical investigation, in which STAT6 signaling was discovered to be involved in some of the brain’s mechanisms, such as the activity of neurons and neuroplasticity." (PMID 36009493, 2022). "However, we propose that STAT6 can be considered as a potential biomarker for depression." (PMID 36009493, 2022).